PAK1 (p21 (RAC1) activated kinase 1)
Diseases named in the same sentence as PAK1 in open-access papers (continued):
Sharing a sentence is not in itself a finding about the gene and the disease.
tumor (continued). "The mouse study showed that the number of mice developing pulmonary metastases 4 weeks after the tumor cell injection was significantly lower in the PAK1‐shRNA group (1 out 10 mice) relative to the scrambled control group (6 out of 10 mice)." (PMID 31872963, 2020). "To further evaluate the effects of PAK1 on other metastasis‐associated processes, we measured colony formation, tumor cell proliferation, and tumor cell‐extracellular matrix (ECM) adhesion in the three PAK1‐shRNA#1 mutants and their scrambled shRNA controls." (PMID 31872963, 2020). "PAK1 is a serine/threonine‐specific protein kinase, which can autophosphorylate and activate itself during tumor development." (PMID 31872963, 2020). "Due its huge impact on tumor survival, PAK1 has also emerged as a promising target for antitumor drug development." (PMID 32863957, 2020). "Using transwell migration assays, we demonstrated that all three PAK1‐silenced cell lines displayed significantly lower tumor cell migration than the parental cell lines." (PMID 31872963, 2020). "PAK-1 is abnormally expressed in various neoplasms, including breast, ovarian, pancreatic, colon and prostate cancers and is involved in tumour cell growth and development of chemoresistance." (PMID 33092251, 2020). "PAK1 has played a vital role in the drug resistance process in multiple tumors, and synergistic inhibition of PAK1 always benefits the tumor treatment." (PMID 32863957, 2020). "On the other hand, PAK1 accelerates angiogenesis in the tumor microenvironment to ensure energy supply." (PMID 32863957, 2020). "Then, phospho‐PAK1 initiates actin polymerization to promote tumor cell motility and metastasis development." (PMID 31872963, 2020). "Consistent with our results, the published microarray data (NCBI/GEO/GSE23400 and GSE20347) also showed that the mRNA expression of PAK1 was much higher in ESCC tissues compared with adjacent non-tumor tissues." (PMID 30971268, 2019). "The combination of gefitinib with an AKT inhibitor (perifosine) or PAK1 inhibitor (IPA-3) almost completely suppresses the tumor burden in nude mice harboring gefitinib resistant cells." (PMID 31660987, 2019). "The tumor volume in the PAK1-knockout HAP1 cell-injected mice was smaller than that in the HAP1 cell-injected mice." (PMID 31658701, 2019). "Overall, these results suggest that proper invadopodia dynamics regulated by PAK1 is required for efficient invasion and metastatic tumor growth." (PMID 30651600, 2019). "In an experimental mouse model of brain metastasis, inhibition of PAK1 significantly reduced overall tumor burden and reduced the average size of brain metastases." (PMID 30651600, 2019). "These factors have been showed to be involved in chemotaxis (CXCR485) and locomotion (ROCK1/2, Acta2, Pak-1, Rac1, and RhoA28) of stromal cells to help migration of these cells to tumor niches." (PMID 31391540, 2019). "We have expected a synergistic effect of alisertib and FRAX1036 on cell cycle and suppression of tumor growth because of more effective suppression of AURKA in the settings of PAK1 inhibition." (PMID 31254157, 2019). "More importantly, Pharmacological inhibition of PAK1 by IPA-3 significantly suppressed tumor growth and lung metastasis of ESCC cells in vivo." (PMID 30971268, 2019). "We show that inhibition of PAK1 inhibits cell proliferation and CSC formation, and tumor growth is significantly reduced in a PAK1-knockout xenograft model." (PMID 31658701, 2019). "We then quantified tumor burden at endpoint, Day 28, using BLI signal and found a significant reduction in total tumor burden in mice injected with PAK1 knockdown cells (1.2 × 105 ± 0.8 radiance) compared to control cells (6.9 × 105 ± 1.8 radiance) (p = 0.02)." (PMID 30651600, 2019).
tumor (continued). "Pharmacological inhibition of AURKA and PAK1 synergistically decreased survival of multiple tumor cell lines, showing particular effectiveness in luminal and HER2-enriched models, and inhibited growth and ERα-driven signaling in a BT474 xenograft model." (PMID 31254157, 2019). "In a rat model, tumor progression was inhibited when the rats were fed with 100 mg/kg of myricetin, which was found to be due to inhibition of the p21 activated kinase-1 (PAK1)." (PMID 31766399, 2019). "Functional studies revealed that the role of PSMA in tumor angiogenesis is part of an autoregulatory loop involving β1-integrin and p21-activated kinase 1 (PAK1)." (PMID 29515776, 2018). "Both strategies down-regulated the expression of αvβ3 and its downstream molecules FAK and PAK1, induced tumor cell apoptosis, and dramatically decreased the ability of tumor cell adhesion and invasion." (PMID 29703238, 2018). "The presence of PAK2 regulates haematopoietic tumour growth in vivo and cannot be compensated for by PAK1." (PMID 28707321, 2017). "Our study demonstrated that PAK1 is upregulated in PCa and regulated by the mTOR signaling pathway and contributes to tumor autophagy." (PMID 28186966, 2017). "The role of PSMA in tumor angiogenesis is part of an autoregulatory loop involving β1-integrin and p21-activated kinase 1 (PAK1)." (PMID 28002805, 2017). "When treated with a PAK1 inhibitor the SCID mice bearing tumour xenografts also had increased size and weight in their spleens." (PMID 28629331, 2017). "The expression of PAK1 in tumor of shRNA was significantly decreased both at mRNA and protein levels in these of Blank and NC." (PMID 28186966, 2017). "Taken together these results indicate that PAK1 is required for tumour initiation and progression in murine intestinal mucosa possibly by affecting the stem-like property of these tumours." (PMID 28629331, 2017). "For example PAK1 activity was increased in 5-FU resistant xenografted CRC tumours with increased expression of stem cell markers, whereas treatment with a PAK1 inhibitor decreased the expression of stem cell markers and sensitized CRC cells to 5-FU." (PMID 28629331, 2017). "From these data, we conclude that PAK2 and, to a lesser extent, PAK1 expression in leukaemic cells controls/delays the proliferation of surrounding endothelial cells, suggesting an in vivo role in tumour angiogenesis." (PMID 28707321, 2017). "PAK1 appears to be involved in the inhibition and/or down-regulation of the immune system in response to tumour development." (PMID 28629331, 2017). "PAK1 knockout decreased both the number of tumours and tumour incidence in the small intestine of 10-week old APC∆14/+ mice." (PMID 28629331, 2017). "Late stage tumours of tissues, such as brain, breast, ovary, pancreas, or colon, display increased PAK1 activity." (PMID 28707321, 2017). "In the present study we demonstrated that tyrosyl phosphorylation of PAK1 stimulates tumor cell metastasis in vivo." (PMID 27542844, 2016). "A recent report shows that PAK1 is a downstream mediator of VEGFR2 in controlling tumor migration and invasion." (PMID 27044328, 2016). "Tumors and lungs were harvested and homogenized and proteins were separated by SDS-PAGE and analyzed for myc-tagged PAK1 to indicate metastasis of the primary tumor into distant tissues." (PMID 27542844, 2016). "The inhibition of either the expression or the activity of Rac1, Pak1 or Rock1 leads to the suppression of tumor cell growth, invasion and metastasis." (PMID 26871290, 2016). "In this study, we found increased PAK1 and phosphorylated PAK1 levels in tumor tissues according to TNM stage progression." (PMID 25675297, 2015). "The present study demonstrated that intratumoral p-PAK1 overexpression significantly correlated with more aggressive tumor behavior and poor prognosis." (PMID 25675297, 2015).
tumor (continued). "Three tumours contained mutations in ERBB2/RAS/RAF/MEK pathway members or regulators: an ARAF mutation in combination with a NCK1 mutation, a PAK1 mutation in combination with a NF1 mutation, and an ERBB2 mutation in combination with a TSC1 mutation." (PMID 26506417, 2015). "Analyses showed that Pak1 expression is increased in a statistically significant manner in all four tumor types, relative to matched normal tissues." (PMID 26555075, 2015). "Studies confirmed that inhibition of PAK1 in human tumors and in vivo tumor models resulted in an anti-tumoral effect." (PMID 26023713, 2015). "After quantifying the protein fragments, an obvious positive correlation was observed between RUFY3 and PAK1 expression in tumor tissue samples (P=0.002), and the Spearman's correlation coefficient was perfect (R=0.661)." (PMID 25766321, 2015). "Here we report that treatment of tumours with ionizing radiation or genotoxic drugs drives p21-activated kinase 1 (PAK1)-mediated phosphorylation of CRAF on Serine 338 (pS338) triggering a kinase-independent mechanism of DNA repair and therapeutic resistance." (PMID 26333361, 2015). "The immunohistochemistry (IHC) staining results showed that expression levels of PAK1 and p-PAK1 were increased in tumor tissues compared with peritumoral tissues." (PMID 25675297, 2015). "We confirmed these findings by evaluating PAK1 expression and kinase activity in paired tumor and peritumoral specimens from 119 RCC patients." (PMID 25675297, 2015). "Here we report that exposing tumours to radiation or genotoxic drugs induces a p21-activated kinase 1 (PAK1)-mediated phosphorylation of CRAF on S338, driving a complex between CRAF and CHK2 to promote DNA repair." (PMID 26333361, 2015). "This bidirectional PAK1/FLNa interaction has been demonstrated to influence actin cytoskeletal structures and enhance tumor cell migration." (PMID 26009991, 2015). "We show for the first time that PAK1 was frequently overexpressed in PESCC and in addition, overexpression of PAK1 was significantly associated with tumor location, metastasis and reduced overall survival, and γH2AX, a DNA damage marker." (PMID 26023713, 2015). "Emerging evidences have suggested that PAK1 plays an important role in carcinogenesis and tumor progression 13,14." (PMID 26377044, 2015). "In terms of direct dysregulation in cancer, PAK1 is amplified, overexpressed or hyperactivated in several tumor subtypes." (PMID 25902869, 2015). "Our recent study has shown that IPA-3 suppressed the growth of HCC tumor in nude mouse, blocked the activation of NF-κB via PAK1 inhibition and attenuated the survival signal of HCC cells." (PMID 25093037, 2014). "These correlations, and those between cytoplasmic VAV3 and tumor size and grade, as well as ERα/PR status, were analogous to those previously observed for nuclear and cytoplasmic PAK1." (PMID 24886537, 2014). "PAK1 overexpression was frequently observed in HCC and significantly associated with more aggressive and metastatic tumor phenotypes as well as advanced tumor stage." (PMID 25093037, 2014). "The p21‐activated kinase 1 (PAK1) plays key roles in cellular processes including proliferation, survival, and motility, and in cell transformation and tumor progression." (PMID 24963032, 2014). "Knockdown of PAK1 suppressed in vivo tumor growth of HBx expressing cells as well as their resistance to anoikis." (PMID 25093037, 2014). "As is not reported previously, we noticed an enhanced expression of PAK1 from adjacent nontumorous tissues and atypical hyperplasia to various degrees of tumors from stage I to III, suggesting a selection for increased PAK1 expression during tumor progression." (PMID 24236193, 2013). "On univariate analysis, PAK1 expression, sex, age, pTNM stage, LN status, histological grade and tumor size were responsible for outcomes of patients who underwent surgical resection." (PMID 24236193, 2013).
tumor (continued). "Our analysis documents that a connection exists between PAK1 expression with the advanced tumor stage, tumor size (> 6 cm), LN metastasis, and resection status." (PMID 24236193, 2013). "Our results show a significant induction of tumoral Rac activity and a trend in increased expression of the Rac downstream effector PAK1 and other tumor promoting molecules following resveratrol treatment." (PMID 23298290, 2013). "The release of inhibition of Pak1 phosphorylation by tumour cells expressing the L1815P and T1795A mutant forms of plexinB1is expected to result in an increase in MAPK signalling and to promote tumour progression." (PMID 22404908, 2012). "We examined PNMT-, NDUFC2-, and MTAP-associated outlying genes that were part of metabolic pathways and also ERBB2-, PAK1-, and CDKN2A-associated outlying genes that were related to the oncogenic/tumor suppressor pathways." (PMID 23383675, 2012). "An important difference between the Pak1 and Pak4 studies is that, in contrast to Pak1, even wild-type Pak4 leads to transformation of mammary epithelial cells and tumorigenesis in mice, and it leads to tumor formation at a high frequency." (PMID 23326684, 2012). "Our recent published work demonstrates a fundamental role for PAK1 in NSCLC biology and provides support for PAK1 as a therapeutic target in this tumor indication." (PMID 21653999, 2011). "The present study showed that Rac1 activity and Pak1 expression were significantly increased in primary tumors and metastatic lymph nodes compared with non-tumor tissues." (PMID 20426825, 2010). "With regard to disease-free survival of the patients who were N0 M0 at the time of nephroureterectomy (92 patients), the mean level of Rac1 activity and Pak1 expression in tumor tissue was 2.55 ± 1.62 and 2.43 ± 1.09, respectively." (PMID 20426825, 2010). "Although Pak1 is well known as a downstream effector of Rac1, there have been few simultaneous analyses of Rac1 and Pak1 expression in human tumor tissues." (PMID 20426825, 2010). "We focused our attention on the small Rho GTPase Rac1 and its effector, the p21-activated protein kinase 1 (Pak1), and the merlin tumor suppressor." (PMID 21085651, 2010). "There have been few reports about the simultaneous analysis of Rac1 and Pak1 in human tumor tissues." (PMID 20426825, 2010). "In this study, we demonstrate that knockout of PAK1 and PAK4 reprograms the immune microenvironment by promoting the activation and infiltration of immune cells, a process associated with normalisation of tumour vasculature." (PMID 40943273, 2025). "The role of PAK1 in the tumor microenvironment has garnered considerable attention." (PMID 40332759, 2025). "Moreover, overactivation of PAK1 is closely related to tumor location, lymph node metastasis, and overall survival." (PMID 39944135, 2025). "Additionally, key proteins in the AKT-mTOR and ERK1/2 pathways and PD-L1 further confirmed that ZMF-25 inhibited tumor growth by blocking PAK1 and HDAC class IIb-mediated cell growth mechanisms." (PMID 40302782, 2025). "Knockout of PAK1 or PAK4 enhanced tumour vasculature normalisation by increasing pericyte coverage." (PMID 40943273, 2025). "This study focuses on Pak1's specific impact on metabolic pathways within tumor cells, which may provide valuable insights into the metabolic adaptations driving PDAC tumorigenesis." (PMID 40090587, 2025). "Interestingly, we did not observe significant changes in MAPK-ERK1/2 pathway activation by active PAK1 expression which has been previously reported in tumor cells." (PMID 40586933, 2025). "PAK1 Knockout inhibited xenografted tumour growth of PC in the immunocompromised SCID mouse model." (PMID 41228228, 2025). "This process may occur via the acetylation of PAK1 (p21-activated kinase 1), which leads to autophagy and tumor proliferation by phosphorylating ATG5, thereby protecting ATG5 from ubiquitination-dependent degradation." (PMID 41294712, 2025).
tumor (continued). "In this study, we focused on exploring the role of Pak1 in mediating tumor cell metabolism." (PMID 40090587, 2025). "Studies have demonstrated a positive correlation between PAK1 expression and immune checkpoint genes (ICPs) in various tumor tissues, suggesting that PAK1 may regulate tumor immune responses through immune checkpoint modulation." (PMID 40332759, 2025). "Furthermore, studies have shown that PAK1, Wnt pathway, tumor immune microenvironment, etc. also play an important role in the development of SCCE." (PMID 39944135, 2025). "In summary, the involvement of Pak1 in tumor cell metabolism represents a complex and multifaceted research area, as global metabolomic data analysis reveals that Pak1 regulates crucial metabolic pathways, including glycolysis and various amino acid metabolism pathways." (PMID 40090587, 2025). "Notably, in all but PAK1, tumor tissue copy number was significantly increased from pooled organoid samples (Mann-Whitney, p < 0.05)." (PMID 38827528, 2024). "Additionally, the Wiki pathway involving RAC1/PAK1's implication in cell proliferation, angiogenesis and tumour growth, and the Panther pathways for inflammation, oxidative stress and apoptosis signalling were also listed." (PMID 39281650, 2024). "Furthermore, we providedin vivoevidence that pTyr-PAK1 stimulates PRL-induced tumor metastasis in mice." (PMID 38660565, 2024). "In addition, PAK1 specific inhibition has been shown to be moderately effective in reducing tumor size and increasing survival of a genetically engineered mouse model of NF2." (PMID 39083549, 2024). "However, when the Ras-Rac-PAK1 pathway, which is related to the actin cytoskeleton, is inhibited, the migration behavior of tumor cells is weakened." (PMID 38410113, 2024). "However, tumours with high PAK1 levels were more sensitive to the combination treatment than tumours with low PAK1 levels, as evidenced by the reduction in final tumour volume (86% versus 72%) and the calculated CDI values." (PMID 37537668, 2023). "Patient and tumour characteristics according to PAK1 copy number." (PMID 37368917, 2023). "We found mean PAK1 CN ≥4<6 in 26 (5.1%) tumours, and CN ≥ 6 in 22 (4.3%) tumours." (PMID 37368917, 2023). "PAK1 protein expression levels have been found to correlate positively with αSMA and Desmin in pancreatic stellate cells (PSCs), which stimulate angiogenesis and facilitate tumour extravasation." (PMID 38067120, 2023). "Our study further analyzed the signal pathways that may performed in the tumorigenesis and revealed the sensitivity of PCSK9 correlated with anti-tumor drugs in tumor treatment and their corresponding targets, such as PAK1, BCL2 and MDM2." (PMID 37860186, 2023). "PAK1 copy number in primary tumours and corresponding axillary lymph node metastases." (PMID 37368917, 2023). "PAK1 has a vital role in the process of tumour angiogenesis." (PMID 38067120, 2023). "In addition to Pak1 involvement in tumor progression, its role in drug resistance has already been described in multiple cancers." (PMID 37258566, 2023). "Zhang Y. and coauthors hypothesized that dual inhibition of HDAC6 and PAK1 could have strong implications for tumor treatment by simultaneously targeting oncogenic metabolic pathways and epigenetic modification." (PMID 38004560, 2023). "In a mouse model of intestinal cancer, PAK1 has been demonstrated to initiate tumor development." (PMID 37190165, 2023). "Phosphorylation of ER by PAK1 may induce tamoxifen-resistance in ER positive tumours and tamoxifen itself may also increase nuclear PAK1 and PAK1 kinase activity." (PMID 37368917, 2023). "Some miRNAs, such as miR-142-3p, inhibit tumor cell migration by restraining Rac1/PAK1." (PMID 37049739, 2023). "In addition to being a member of the PP6 holoenzyme, ANKRD52 inhibits tumor progression through PP6c-mediated dephosphorylation of PAK1." (PMID 37521466, 2023).